STON2 (stonin 2)
Diseases named in the same sentence as STON2 in open-access papers:
STON2 is named in the same sentence as 14 diseases in open-access papers, as found by Europe PMC text mining. Sharing a sentence is not in itself a finding about the gene and the disease. The quoted sentences say what the papers report.
ovarian carcinoma (7 papers, 2017 to 2025). A malignant neoplasm originating from the surface ovarian epithelium. "STON2 modulates stem-like properties in ovarian cancer cells, which are highly associated with poor prognosis and invasion." (PMID 37719881, 2023). "Due to all of these data, abnormal STON2 expression was associated with intraperitoneal metastasis and recurrence, as well as a poor OS in ovarian cancer patients, suggesting that STON2 overexpression is associated with a poor prognosis." (PMID 28758939, 2017). "This study has, for the first time, revealed that STON2 protein expression was associated with the prognosis of ovarian cancer." (PMID 28758939, 2017). "Over 70 proteins were found most differentially expressed, and among them, stonin 2 (STON2) was suggested to downregulate the stemness of the ovarian cancer cell which is characterized by EMT-related markers." (PMID 31781477, 2019). "Interestingly, upregulation of stonin 2 (an adaptor-like protein that regulates endocytic complexes and D2 internalization) is commonly associated with progression and unfavorable prognosis of epithelial ovarian cancer, being correlated with intestinal and intraperitoneal metastasis." (PMID 31703453, 2019). "Here, we present novel observations, which indicate that STON2 is involved in modulating stemness in ovarian cancer cells." (PMID 30518424, 2018). "Further random examinations of specimen sections from the paraffin-embedded blocks of ovarian cancer patients confirmed that STON2 and MUC1 expression correlated negatively." (PMID 30518424, 2018). "This provides a contrast to a previously published finding that STON2 overexpression is correlated with unfavorable prognosis in 89 ovarian cancer patients." (PMID 30518424, 2018). "The paired expression of STON2 and MUC1 in ovarian cancer specimens was also detected revealing the prognostic value of STON2 expression to be highly dependent on MUC1 expression." (PMID 30518424, 2018). "We show that STON2 negatively modulates the stem-like properties of ovarian cancer cells, which are characterized by sphere formation, a CD44+CD24− ratio, and by CSC- and epithelial mesenchymal transition (EMT)-related markers." (PMID 30518424, 2018). "STON2 knockdown promotes stem-like properties in ovarian cancer cells and its overexpression suppresses MUC1-induced sphere formation in OCSCs, in which DNMT1-mediated methylation in the promoter region of MUC1 has been confirmed to be modulated by STON2." (PMID 30518424, 2018). "RNA-sequencing (RNA-seq) and pyrosequencing were used to reveal the mechanism by which STON2 negatively modulates the stem-like properties of ovarian cancer cells." (PMID 30518424, 2018). "As STON2 modulates stem-like properties in ovarian cancer cells, we attempted to determine the downstream targets of STON2." (PMID 30518424, 2018). "In conclusion, STON2 plays an important role in the progression and prognosis of ovarian carcinoma, especially in platinum resistance, intraperitoneal metastasis, and recurrence." (PMID 28758939, 2017). "Despite the fact that the STON2 protein plays an important role in endocytosis, there was little research investigating the relationship between STON2 and tumors, particularly ovarian cancer, which still remains an important subject to be explored." (PMID 28758939, 2017). "We took advantage of real-time PCR, Western bloting, and immunohistochemical analyses to evaluate STON2 expression in ovarian cancer and in normal control tissues at the mRNA and protein levels." (PMID 28758939, 2017). "Real-time PCR and Western blot analyses were used to determine the expression of STON2 mRNA and protein in ovarian cancer cell lines (CAOV3, COV362, COV504, EFO-27, A2780, OVCAR4, SKOV3, and TOV-21G) and in normal cells (HOSEpiC)." (PMID 28758939, 2017). "The results of the real-time PCR and Western blot analyses revealed that all of the ovarian cancer cell lines overexpressed STON2 protein and mRNA." (PMID 28758939, 2017).
ovarian carcinoma (continued). "As we predicted, the STON2 mRNA and protein levels were obviously higher in most of the ovarian cancer tissues than in normal ovarian tissues." (PMID 28758939, 2017). "Considering the high expression of STON2 in ovarian cancer, we further investigated its correlation with the clinical characteristics of ovarian cancer in 89 cases by immunohistochemistry." (PMID 28758939, 2017). "STON2 significantly increased in the ovarian cancer cell lines and tissues compared to the normal ones." (PMID 28758939, 2017). "Simultaneously, the results of the immunohistochemical staining also provided strong evidence that the STON2 protein, which was intensively expressed in the cytoplasm, was upregulated in the ovarian cancer tissues compared to the normal ovarian tissues." (PMID 28758939, 2017). "Here, we inspected STON2 expression in ovarian cancer cell lines and tissues and in normal control cells and tissues." (PMID 28758939, 2017). "This suggests that MUC1 acts downstream of STON2 in ovarian cancer cells." (PMID 30518424, 2018). "However, significantly lower STON2 immunoreactivity was detected in poorly differentiated ovarian cancer (P = 0.000)." (PMID 30518424, 2018). "Our results imply that STON2 may negatively regulate stemness in ovarian cancer cells via DNMT1-MUC1 mediated epigenetic modification." (PMID 30518424, 2018). "Thus, STON2 has potential for use as a therapeutic target to enhance the dopamine treatment’s efficacy in ovarian cancer." (PMID 28758939, 2017). "Taken together, these results suggest that as an independent prognostic factor, STON2 may contribute to the prognosis of ovarian cancer." (PMID 28758939, 2017). "The clinical significance of STON2 expression in ovarian cancer was statistically analyzed." (PMID 28758939, 2017). "Therefore, in this study we aimed to investigate the characteristics of STON2 expression and its clinicopathological implications in ovarian cancer." (PMID 28758939, 2017). "In the light of all the analyses, we concluded that STON2 may be vital in the progression as well as the prognosis of ovarian cancer." (PMID 28758939, 2017). "Overall, for the first time, the results of this study suggested that STON2 is upregulated in ovarian cancer and its expression is correlated with intraperitoneal metastasis, intestinal metastasis, intraperitoneal recurrence, ascites with tumor cells, CA153 level, and poor prognosis in EOC patients." (PMID 28758939, 2017). "Together, these results suggest that STON2 may play an important role in disease development in ovarian cancer." (PMID 28758939, 2017). "Therefore, STON2 may be used as a NACT predictor for ovarian cancer patients to provide better guidance for individual treatment strategies, indicating that neoadjuvant chemotherapy may be more available for EOC patients with STON2 overexpression." (PMID 28758939, 2017). "Thus, STON2 may directly or indirectly participate in the invasion of cancers, including ovarian cancer." (PMID 28758939, 2017). "In addition, multivariate Cox regression analysis further revealed that STON2 protein expression level (p = 0.010), intraperitoneal recurrence (p = 0.011), and platinum resistance (p = 0.003) were indeed independent prognostic factors of ovarian cancer." (PMID 28758939, 2017). "On the other hand, the overexpression of STON2 has also been observed in oral squamous cell carcinoma (OSCC) tissues, and its overexpression in ovarian cancer-derived cell lines induces a higher rate of proliferation and migration." (PMID 40508156, 2025). "In this study, we also showed that parent genes such as BCLAF1, FBLN1, ARHGAP23, STON2, UBQLN4, and ATP2B1 were significantly positively correlated with the survival rate of patients with ovarian cancer." (PMID 35978436, 2022). "We found that the expression of six genes (BCLAF1, FBLN1, ARHGAP23, STON2, UBQLN4, and ATP2B1) had a significant positive correlation with the survival rate of patients with ovarian cancer." (PMID 35978436, 2022).
ovarian carcinoma (continued). "Our findings suggest that STON2 depression up-regulates MUC1 expression, along with inhibition of DNMT1, in a process that contributes to the maintenance of stem-like properties in ovarian cancer cells." (PMID 30518424, 2018). "The reason for such an inconsistency is unclear, but our paper certainly represents a fairly comprehensively exploration of the prognostic value of STON2 expression and MUC1 expression in ovarian cancer." (PMID 30518424, 2018). "The identified protein network revealed that STON2 modulate stemness in ovarian cancer cells via epigenetic effectors such as DNMT1, and therefore, STON2 has a role in ovarian cancer biology and could represent a therapeutic target." (PMID 31781477, 2019). "Taken together, these observations provide evidence that STON2 acts as a negative modulator via the MUC1-mediated pathway in ovarian cancer." (PMID 30518424, 2018). "STON2, therefore, is involved in OCSC biology and may represent a therapeutic target for innovative treatments aimed at ovarian cancer eradication." (PMID 30518424, 2018). "In the present study, we found that analysis of STON2 in isolation did not have any prognostic value in ovarian cancer." (PMID 30518424, 2018). "STON2, is therefore involved in OCSC biology and may represent a therapeutic target for innovative treatments aimed at ovarian cancer eradication." (PMID 30518424, 2018). "In summary, we observed for the first time that STON2 acts as a negative modulator in ovarian cancer cells via DNMT1/MUC1-mediated epigenetic mechanisms." (PMID 30518424, 2018). "However, thus far, no research has specifically investigated the role of STON2 on tumor progression and prognosis in ovarian cancer." (PMID 28758939, 2017). "Indeed, stonin 2 was upregulated in multiple ovarian cancer cell lines (CAOV3, COV362, COV504, EFO-27, A2780, OVCAR4, SKOV3, and TOV-21G) compared to non-tumorigenic human ovarian surface epithelial cells (HOSEpiC), and in ovarian cancer tissue samples compared to control conditions." (PMID 31703453, 2019).
schizophrenia (5 papers, 2013 to 2025). A major psychotic disorder characterized by abnormalities in the perception or expression of reality. "In this study, we used the imaging genetics approach to examine the effects of Ser307Pro and Ala851Ser polymorphisms of the STON2 gene on the cortical surface area in patients with schizophrenia and healthy controls." (PMID 23785397, 2013). "The STON2 gene is located on chromosome 14q, which is a candidate region implicated in linkage studies of schizophrenia." (PMID 23785397, 2013). "This study aims to explore the relationship between two functional polymorphisms (Ser307Pro and Ala851Ser) of STON2 gene and the cortical surface area in first-episode treatment-naïve patients with schizophrenia and healthy controls." (PMID 23785397, 2013). "So this finding partially supports the positive association of the human STON2 gene with schizophrenia, as indicated in the study by Luan." (PMID 23785397, 2013). "Genotype distributions and allele frequencies of Ser307Pro and Ala851Ser polymorphisms of STON2 gene among patients with schizophrenia and healthy controls." (PMID 23785397, 2013). "Two exonic single-nucleotide polymorphisms (SNPs) of the STON2 gene were associated with schizophrenia in a Chinese population." (PMID 23785397, 2013). "In summary, our study provided preliminary evidence that the functional variant of the STON2 gene altered the right inferior temporal cortical surface area and contributed to the pathogenesis of schizophrenia." (PMID 23785397, 2013). "Evidence shows that STON2 gene is associated with synaptic function and schizophrenia." (PMID 23785397, 2013). "The present study demonstrated that the functional variant of the STON2 gene could alter cortical surface area on the right inferior temporal and contribute to the pathogenesis of schizophrenia." (PMID 23785397, 2013). "We hypothesized that functional genetic variants of STON2 gene, Ser307Pro and Ala851Ser, was associated with the cortical surface area of patients with schizophrenia, and could provide evidence that the STON2 gene is related to the development of schizophrenia." (PMID 23785397, 2013). "Deletion covering STON2, which encodes the endocytic adaptor stonin 2, has been already found in familial GTS, and polymorphisms have been associated with schizophrenia." (PMID 38891944, 2024). "The present study aimed to investigate the relationship between the genetic of the STON2 gene and the cortical surface area in patients with schizophrenia and healthy controls." (PMID 23785397, 2013).
keratoconus (3 papers, 2020 to 2024). A degenerative, structural disorder of the eye, characterized by a cone-shaped protrusion of the cornea. "We anticipate that further research on ZNF469 and STON2 will reveal pleiotropic effects for these genes in terms of corneal thickness and the risk for keratoconus development." (PMID 32737415, 2020). "We also identified STON2 rs2371597 (located at chromosome14q31) as a keratoconus-susceptibility SNP." (PMID 32737415, 2020). "In this two-stage genome-wide association study (GWAS) of CCT, we identified a locus for CCT, namely STON2 rs2371597 (P = 2.32 × 10−13), and confirmed a significant association between STON2 rs2371597 and keratoconus development (P = 0.041)." (PMID 32737415, 2020). "In summary, we identified two keratoconus-susceptibility loci, STON2 and SMAD3, by integrating conventional GWAS and artificial intelligence, using WDD." (PMID 32737415, 2020). "To evaluate the possible association between STON2 rs2371597 and keratoconus, we conducted a case-controlled study using 179 keratoconus patients, regardless of age, sex, or physical impairment, from the Yokohama City University and 11,084 Japanese healthy controls." (PMID 32737415, 2020). "The eQTL data revealed that the effect size of rs2371597 on STON2 expression was strongest in skeletal muscle, which is rich in collagen, a protein that reportedly plays a key role in keratoconus pathogenesis." (PMID 32737415, 2020). "We found that the STON2 rs2371597 allele was significantly associated with CCT and keratoconus, as well as significantly altered STON2 expression in human tissues." (PMID 32737415, 2020). "STON2 and SMAD3 have roles in extracellular matrix (ECM) remodeling, so these variants may contribute to the stromal ECM changes described in keratoconus." (PMID 38984114, 2024). "Although biological studies examining the role of STON2 in human corneal tissue are required to prove our hypothesis, pathways involving STON2 may serve as targets for treating keratoconus by controlling basal cell degeneration." (PMID 32737415, 2020). "Although no previous reports have investigated the expression of STON2 in human corneal tissue, we speculate that STON2 may play an important role in keratoconus development by interacting with extracellular matrix remodelling." (PMID 32737415, 2020). "They found the STON2 rs2371597 and SMAD3 rs12913547 loci to be involved in keratoconus development." (PMID 38984114, 2024).
epilepsy (2 papers, 2016 to 2025). A brain disorder characterized by episodes of abnormally increased neuronal discharge resulting in transient episodes of sensory or motor neurological dysfunction, or psychic dysfunction. "Mice with a genetic ablation of both SV2A/B and stonin-2 display a worse seizure phenotype, and more prominent lethality than SV2A/B knockout mice alone suggesting stonin-2 dysfunction may increase susceptibility to epilepsy." (PMID 26903854, 2016).
neuroblastoma (1 paper, 2017). Neuroblastoma (NB) is the most common solid, extracranial childhood tumor. "The μ-HD of stonin 2 was necessary for the sorting of stonin 2 to the presynaptic terminals in cultured hippocampal neurons and to the plasma membrane upon co-expression with Syt1 in a neuroblastoma cell line." (PMID 29379416, 2017).
cancer (4 papers, 2017 to 2022). A tumor composed of atypical neoplastic, often pleomorphic cells that invade other tissues. "In these cases, while NR2F1 is associated with cancer cell dormancy, DNAJB4 acts as a suppressor for cancer cell metastasis and STON2 negatively modulates tumor stemness and tumorigenesis." (PMID 34722496, 2021). "Interestingly, here we showed that NANOG and c-MYC expression, as stemness-associated factors, were detected in these OCSCs and that their cancer stem-like properties were negatively regulated by STON2 expression." (PMID 30518424, 2018). "Therefore, STON2 might play an important role in the invasion of EOC, as well as serve as a novel cancer therapeutic drug target and biomarker that can predict an unfavorable prognosis in EOC patients." (PMID 28758939, 2017). "Thus, STON2 expression can serve as a predictor of intraperitoneal metastasis and recurrence in EOC patients and can be used to provide more precise cancer staging as well as guide a more radical personalized therapy by more effectively reducing the mortality rate of EOC patients." (PMID 28758939, 2017).
tumor (3 papers, 2017 to 2021). "Stonin-2 overexpression was correlated with unfavorable prognosis and tumor invasion in epithelial ovarian cancer." (PMID 34439329, 2021). "In the 89 EOC samples tested, STON2 expression was significantly correlated with intraperitoneal metastasis, intestinal metastasis, intraperitoneal recurrence, ascites containing tumor cells, and CA153 level." (PMID 28758939, 2017). "Additionally, we found that STON2 overexpression indicated a tendency to have undergone neoadjuvant chemotherapy and the presence of ascites containing tumor cells, which is one of the indications for neoadjuvant chemotherapy." (PMID 28758939, 2017). "In addition, our study also identified NR2F1, DNAJB4, and STON2 as the downregulated genes in SN, which could suppress tumor growth and metastasis." (PMID 34722496, 2021). "We also assessed the prognostic value of STON2 expression in EOC patient subgroups stratified by serum biomarker levels such as CA153, CA199, intraperitoneal metastasis, ascites with tumor cells, neoadjuvant chemotherapy, intraperitoneal recurrence and so on." (PMID 28758939, 2017). "Stonin 2 (STON2), which functions in adjusting endocytotic complexes, is probably involved in the monitoring of the internalization of dopamine D2 receptors which have an inhibitory action of dopamine on tumor progression." (PMID 28758939, 2017). "Overexpression of STON2 in patients with EOC was found to be significantly related with intraperitoneal metastasis, intestinal metastasis, intraperitoneal recurrence, ascites with tumor cells, and a high CA153 level." (PMID 28758939, 2017).
renal disease (1 paper, 2015). "There was attenuation of association of SNPs near RRM1|STIM1 and STON2|SEL1L after adjustment (although still significant at p<0.05, unadjusted for multiple comparisons), suggesting that these SNPs have effects on SCDA levels mediated through these clinical factors, in particular renal disease." (PMID 26540294, 2015).
STON2 also shares sentences with these, for which no sentence is quoted: Allergy (1 paper); Alzheimer disease (1); asthma (1); autoimmune disorders (1); lymph node metastasis (1); oral squamous cell carcinoma (1).